MMP9 (matrix metallopeptidase 9)
Diseases named in the same sentence as MMP9 in open-access papers (continued):
Sharing a sentence is not in itself a finding about the gene and the disease.
gastric cancer (continued). "With integrated bioinformatics analysis, BGN, LOX, MMP-9, SERPINE1, and TGFB1 proteins have been selected as suitable diagnostic biomarkers for noninvasive to invasive stages of gastric cancer." (PMID 34054953, 2021). "In gastric cancer, miR-145 directly targets transcription factor specificity protein 1SP1 to down-regulate the expression of matrix metalloproteinase-9 (MMP-9) and Cyclin D1, inhibiting cell growth and invasion." (PMID 34659567, 2021). "RTEF-1 was reported to be regulated by PI3K/AKT/β-catenin signaling, which activated the transcription of MMP9, a key molecule that promotes gastric cancer cell proliferation and metastasis." (PMID 33713163, 2021). "MMP-9 expression in gastric cancer was significantly correlated with the grade, depth of invasion, and TNM stage (p-value = 0.003, 0.019, and 0.025, respectively)." (PMID 34707964, 2021). "TNF-α-induced MMP-9 secretion from mesothelial cells plays an important role in the metastatic dissemination of gastric cancer." (PMID 34016788, 2021). "When melatonin was used, the IL-1β/NF-κB/MMP-2/MMP-9 genes' expression and also invasion of gastric cancer cells reduced significantly." (PMID 34054953, 2021). "In our previous work, we demonstrated that LPE can reduce IL-6-induced migration/invasiveness and MMP-9/2 up-regulation in some gastric cancer cell lines." (PMID 34885656, 2021). "The MMP-9 expression in gastric cancer was identified by immunohistochemistry using a monoclonal antibody in paraffin-embedded sections, correlated with various clinicopathological parameters, and statistically analyzed." (PMID 34707964, 2021). "Naringenin induces apoptosis of gastric cancer SGC7901 cells by decreasing the expression of MMP9 by downregulating the AKT pathway." (PMID 34899944, 2021). "The expression of MMP-9 is regulated by the Akt signaling pathway, and promotes cell invasion in many types of cancers, such as head and neck squamous cell carcinoma, gastric cancer and renal cancer." (PMID 33780455, 2021). "MMP-9 present in the extracellular matrix plays a vital role in tumor invasion and progression of gastric cancer by acting as a key messenger between tumor cells, stromal cells, and cytokines which forms the tumor microenvironment." (PMID 34707964, 2021). "We investigated MMP-2 and MMP-9 expression and HERE-2/neu overexpression in 48 gastric cancer patients referred to Afzalipour Hospital, associated with Kerman Medical University." (PMID 33773545, 2021). "The objective is to study the expression of MMP-9 (matrix metalloproteinase-9) in gastric cancer and to correlate it with the existing prognostic factors." (PMID 34707964, 2021). "HOXC6, as an important transcription factor, enhances the MMP-9 activity and is involved in increasing the metastasis of gastric cancer." (PMID 34054953, 2021). "MMP-2 and MMP-9 are members of the MMPs family and have been reported to be overexpressed in gastric cancer." (PMID 33758617, 2021). "Mechanistically, sorcin silencing effectively decreased the expression of matrix metalloproteinases 2 and 9 (MMP2 and MMP9), and eventually suppressed gastric cancer metastasis." (PMID 34869449, 2021). "Matrix-metalloproteinase-9 (MMP-9) is expressed by a wide range of cells and plays a significant role in the regulation of the tumor microenvironment of various cancers including gastric cancer." (PMID 34707964, 2021). "The recently research discovered that, NEDD8-Activating Enzyme (NEDD8-Activating Enzyme, NAE) inhibitor MLN4924 can significantly inhibit the migration of gastric cancer cells through transcriptional activation of E-cadherin and inhibition of MMP-9." (PMID 34422902, 2021). "Ectopic expression of MICAL2 augmented MRTF-A levels in the nucleus, and promoted the activation of CDC42, MMP9 expression, and gastric cancer cell migration." (PMID 33842533, 2021).
gastric cancer (continued). "Recently, anti-MMP9 Fab has been generated by digesting a humanized monoclonal anti-MMP9 antibody, GS-5745, with an enzyme; its structure, function, and positive effects in the treatment of ulcerative colitis and gastric cancer was shown." (PMID 34577904, 2021). "To elucidate the mechanism by which KLF5 promotes proliferation and migration in gastric cancer, we next studied the expression levels of CyclinD1 and MMP9 proteins." (PMID 34367275, 2021). "This implies that most of the advanced gastric carcinoma and tumors with serosal invasion show increased MMP-9 expression." (PMID 34707964, 2021). "The overexpression of Twist1 and MMP-9 affects the overall survival and metastasis of human gastric carcinoma patients." (PMID 33567682, 2021). "MMP-9 expression is significantly increased in poorly differentiated gastric carcinomas, tumors with serosal perforation, and TNM stage III-IV tumors." (PMID 34707964, 2021). "In gastric carcinoma, overexpression of MMP-9 is correlated with increased metastatic potential, TNM staging, lymphatic invasion, depth of tumor invasion, and overall survival." (PMID 34707964, 2021). "RPSA positively regulates expressions of UPA and MMP-9 in gastric cancer, which is vital for the tumor matrix and basement membrane." (PMID 32964027, 2020). "In terms of tumor progression and metastasis, AHR activation enhanced gastric cancer cell invasiveness, in part by induction of MMP-9 expression." (PMID 32907554, 2020). "The result demonstrated that PIN1 significantly promotes the expression of cyclin D1, MMP2, MMP9, β-catenin, and N-cadherin, while inhibits E-cadherin expression in gastric cancer." (PMID 32703934, 2020). "The increased expression of HOXC6 in gastric cancer cell lines significantly activated extracellular signals regulating kinase signal transduction and MMP9 upregulation, which promoted the migration and invasion of gastric cancer cells." (PMID 32509568, 2020). "TAMs of gastric cancer released MMP9, which promoted cancer cell migration through an induction of the master regulator of EMT, Snail." (PMID 32283687, 2020). "Previous studies have found that apatinib plays a role in the downregulation of MMP-2 and MMP-9 in gastric cancer." (PMID 32685465, 2020). "The validation study showed that SOX3 is overexpressed in cancer tissues, and its levels are associated with poor outcomes for stomach cancer, and that SOX3 promotes gastric cancer cell invasion and migration through MMP9." (PMID 32363730, 2020). "Evaluation of urine samples from individuals with gastric cancer versus healthy controls also revealed that urinary MMP-9/NGAL complex was a potential biomarker of early-stage gastric cancer." (PMID 32046329, 2020). "In the early stages of gastric cancer metastasis, MMP-9 secreted from TAMs induced EMT by upregulation of transcription factor Snail controlled by PI3K/AKT activation." (PMID 32283687, 2020). "We collected fresh cancer specimens from gastric cancer patients who underwent surgery to quantitate the protein expression levels of LOX and MMP-9 in gastric cancer tissues." (PMID 31777578, 2019). "In other tumors, such as gastric cancer, MMP9 plasma levels correlated better with disease progression and lymph node invasion than the serum levels." (PMID 31191742, 2019). "CaMKII activity is essential for this process, as expression of a constitutively active (H282R) mutant enhances gastric cancer cell migration and invasion by upregulating matrix metalloproteinase-9 (MMP-9)." (PMID 30621060, 2019). "The consensus-expressed PNI gene signature (CXCL8 and MMP9) in gastric cancer is identified on the basis of meta-analyzed GEO datasets." (PMID 31681401, 2019). "Studies have confirmed that in esophageal cancer and gastric cancer, MMP9 and MMP2 act as targets of NF-κB, which promote the invasion and metastasis of tumor cells." (PMID 31110076, 2019).
gastric cancer (continued). "This low dose of ellagic acid reduced acidity-promoted expression of MMP7 and MMP9 and inhibited the migrating and matrigel-infiltrating capability of gastric cancer cells, indicating the inhibitory action of ellagic acid against acidity-enhanced invasiveness." (PMID 31835645, 2019). "HOXC6 promotes the migration, invasion, and progression of gastric cancer by upregulating Matrix metalloproteinase 9 (MMP9)." (PMID 30993034, 2019). "Immunohistochemistry was used to quantitate the expression levels of LOX and MMP-9 in gastric cancer tissues." (PMID 31777578, 2019). "The relative expression levels of LOX and MMP-9 were 0.052 ± 0.025 and 0.086 ± 0.043, respectively, in the tissues from the 49 gastric cancer patients." (PMID 31777578, 2019). "The formation of the VGLL1–TEAD4 complex activates the transcription of MMP9, which then promotes proliferation and metastasis in gastric cancer cells." (PMID 31816819, 2019). "Subsequently, MMP9, a key molecule in gastric cancer, was explored as one of target genes that were transcribed by VGLL1-TEAD4 complex, a component of the transcription factor." (PMID 31816819, 2019). "Matrix metalloproteinase 9 (MMP-9) is overexpressed in various tumors and related to poor disease prognosis in oral and gastric cancers." (PMID 30754703, 2019). "Here, we present the regulation mechanism of VGLL1 to induce MMP9 expression that promotes gastric cancer malignancy." (PMID 31816819, 2019). "We found that LOX and MMP-9 expression were positively correlated in the gastric cancer tissues of these 49 patients." (PMID 31777578, 2019). "Immunohistochemistry was used to quantitate the protein expression levels of LOX and MMP-9 in gastric cancer tissues and to analyze their correlation." (PMID 31777578, 2019). "Zhen et al50 also indicated that knockdown of EGFR reduced cell invasion of gastric cancer and led to decreased expression of MMP‐9." (PMID 31638339, 2019). "PRL-3 can up-regulate the expression of MMP-2 and MMP-9, which promote peritoneal metastasis of gastric cancer cells." (PMID 31546234, 2019). "In this research, consensus-expressed CXCL8 and MMP9 are identified in gastric cancer, and a higher coexpression can predict poor disease-free survival." (PMID 31681401, 2019). "This study detected that the overexpression of IFT80 increased the expression of p75NGFR and MMP9 in SGC-7901 gastric cancer cells, indicating that IFT80 overexpression increased the invasion of gastric cancer." (PMID 30453504, 2018). "Previous studies showed that MMP-2 and MMP-9 were overexpressed in gastric cancer, which accelerated the invasion of tumor cells in vitro and in vivo." (PMID 30150551, 2018). "In this study, we evaluated the expression of MMP9 in gastric cancer cell lines, and studied its effect on gastric cancer cell invasion." (PMID 30453504, 2018). "In conclusion, the present study strongly suggests that TNF-α-induced MMP-9 secretions from mesothelial cells play an important role in the metastatic dissemination of gastric cancer." (PMID 30544870, 2018). "In addition to these effects on cancer cells, it seems important that the phenotypic changes of mesothelial cells induced by TNF-α, especially the enhancement of MMP-9 secretion, may cause peritoneal metastasis, and thus a poor prognosis for patients with gastric cancer." (PMID 30544870, 2018). "Here, we present the first evidence that IFT80 is significantly highly expressed in gastric cancer cells, and we also show that IFT80 increases the invasion and metastasis of gastric cancer by the upregulation of p75NGFR and MMP-9." (PMID 30453504, 2018). "Previous studies indicated that the elevated expression of MMP2 and MMP9 correlated with the invasive capability of gastric cancer cells." (PMID 28994231, 2018). "Since MMP9 plays an important role in cell proliferation, invasion, and migration, it can thereby participate in the process of gastric cancer metastasis." (PMID 30453504, 2018).
gastric cancer (continued). "For example, TNF-α treatment of human gastric cancer cells was shown to increase MMP-9 mRNA and protein expression levels." (PMID 30544870, 2018). "Our results indicated that IFT80 enhanced the invasion ability in gastric cancer via upregulation of MMP9 protein expression." (PMID 30453504, 2018). "In short, these data suggest that the reduction in MMP9 protein expression and inhibition of gastric cancer cell metastasis was at least partially mediated by the downregulation of p75NGFR." (PMID 30453504, 2018). "Taken together, these results suggested that the reduction in MMP9 protein expression and inhibition of the metastatic ability of gastric cancer cells was at least partially mediated by the downregulation of p75NGFR." (PMID 30453504, 2018). "We have previously studied the interaction of gastric carcinoma cells with the mesothelium and found that the integrin-dependent adhesion of carcinoma cells to the submesothelial matrix promotes MMP-9 secretion from cancer cells." (PMID 30544870, 2018). "We also present evidence showing that MMP-9 secreted from mesothelial cells plays a significant role in the invasion of gastric carcinoma cells." (PMID 30544870, 2018). "The relationship of FOXO6 and MMP-9 expression was verified by IHC methods in serial sections of gastric cancer samples." (PMID 28404958, 2017). "The relationship between the expression of spondin-2 and MMP-9, clinicopathological/prognostic value in gastric cancer was examined." (PMID 28060752, 2017). "In previous studies, Tan-IIA decreased migration or invasion through inhibiting MMP-9/-2 secretion in gastric cancer and osteosarcoma." (PMID 28757590, 2017). "Few studies have analyzed MMP-9 expression in PA and in other tumours such as prostate and gastric cancer." (PMID 28194042, 2017). "The correlation between FOXO6 expression with MMP-9, clinicopathological/prognostic value in gastric cancer was examined." (PMID 28404958, 2017). "In summary, the present study demonstrates that AEG‐1 promotes EMT and metastasis of gastric cancer through upregulation of eIF4E‐mediated expression of MMP‐9 and Twist." (PMID 28661037, 2017). "Overexpression of TMPRSS4 in AGS and MKN-45 gastric cancer cells down-regulated the level of IκBα and induced nuclear NF-κB accumulation, enhanced expression and secretion of MMP-9, and promoted cell migration and invasion." (PMID 28350359, 2017). "It was demonstrated that downregulation of cadherin-17 induced inactivation of NFkB signaling pathway with the reductions of downstream proteins including VEGF-C and MMP-9 and suppressed proliferation, adherence, and invasion in gastric cancer." (PMID 28197418, 2017). "Spondin-2 and matrix metallopeptidase 9 (MMP-9) expression was detected by immunohistochemistry in 174 gastric carcinoma tissues." (PMID 28060752, 2017). "The expression of FOXO6 and matrix metallopeptidase 9 (MMP-9) was assessed by immunohistochemistry in 192 gastric carcinoma specimens." (PMID 28404958, 2017). "Recently, several studies have indicated that IL-32 induces the expression of MMP-2 and MMP-9 in gastric cancer and lung adenocarcinoma." (PMID 27589563, 2016). "miR-15b is also shown to mediate the apoptotic effects of the anti-cancer drug dihydroartemisinin in gastric cancer cells by downregulation of MMP9." (PMID 27070581, 2016). "(vi) Furthermore, 17β‐estradiol inhibits the expression of IL‐8‐Src signalling downstream invasive proteins MMP9, tPA and uPA in human gastric cancer cells." (PMID 26945908, 2016). "In the present study, the expression of HIF-1α, MMP-2, MMP-9, bFGF and uPA was detected in order to further reveal the underlying mechanism of the function of the KAI1 gene in gastric cancer." (PMID 26622792, 2015). "It has been reported that MMP9 correlates with the invasion, metastasis and angiogenesis of gastric cancer." (PMID 25638174, 2015).
gastric cancer (continued). "Further, with the MEK-dominant negative plasmid pMCL-K97M, JNK-dominant negative plasmid pMCL-TAM67 and p38 MAPK-dominant negative plasmid pMCL-mP38, we confirmed the critical roles of ERK and JNK in MMP-9 expression in gastric cancer AGS cells." (PMID 25875631, 2015). "BTG3 overexpression in vitro decreased migration, invasion and lamellipodia formation of gastric cancer cells with a down-regulated expression of MMP-9 and VEGF." (PMID 25904053, 2015). "For intestinal type gastric cancer there was a weak correlation of MMP9 with expression of mTOR in the tumor center." (PMID 26652716, 2015). "We examined the effects of chrysin on MMP-9 expression and activity via RT-PCR, zymography, promoter study, and western blotting in human gastric cancer AGS cells." (PMID 25875631, 2015). "A previous study by our group indicated that hypoxia is able to increase HIF-1α expression, which upregulates MMP-9 and uPA receptor expression in gastric cancer cells, resulting in increased adhesion, migration and invasion." (PMID 25997455, 2015). "High expression levels of MMP-9 in gastric cancer positively correlate with tumor aggressiveness and have a significant negative correlation with patients’ survival times." (PMID 25875631, 2015). "The expression rate of MMP-9 was 86.67% (39/45) in the gastric carcinoma tissues, 26.67% (12/45) in the distal gastric mucosa tissues and 10% (1/10) in the healthy gastric mucosa tissues." (PMID 25621068, 2015). "The present report identified that MMP-9 expression was markedly higher in the gastric carcinoma tissue (86.67%) than in the adjacent healthy tissue (10.00%)." (PMID 25621068, 2015). "The expression level of MMP-9 in gastric carcinoma tissues and the preoperative serum was higher when compared with the healthy tissues." (PMID 25621068, 2015). "H&E and immunohistochemical staining for MMP-9 was observed in the majority of gastric carcinoma tissues." (PMID 25621068, 2015). "In the current study, the expression of MMP-9 in gastric carcinoma samples was analyzed and the correlation between preoperative serum levels of the MMP-9 protein and the clinicopathological characteristics of gastric carcinoma was investigated." (PMID 25621068, 2015). "The mean preoperative serum MMP-9 protein levels in gastric carcinoma patients (0.41±0.26 μg/ml) was significantly higher than those of the control group (0.15±0.04 μg/ml; P<0.05)." (PMID 25621068, 2015). "The present report investigated the correlation between the expression levels of matrix metalloproteinase (MMP)-9 in gastric carcinoma patients and the clinicopathological characteristics." (PMID 25621068, 2015). "The mean level of MMP-9 mRNA in the gastric carcinoma tissues (0.42±0.65) was significantly higher than in the distal (0.22±0.76; P<0.05) and control tissues (0.03±0.06; P<0.05)." (PMID 25621068, 2015). "Semi-quantitative RT-PCR identified MMP-9 expression in 48.9% (22/45) of the gastric carcinoma tissues, 13.3% (6/45) of the distal gastric mucosa tissues (>5 cm from the gastric tumor) and 10% (1/10) of the healthy gastric mucosa control tissues." (PMID 25621068, 2015). "We further explored the influence of tumor invasiveness on the prognostic value of HSP60 in gastric cancer by using MMP-9 as an indicator for the invasive potential of individual tumor cells." (PMID 25207654, 2014). "EMT in gastric cancer involves a Shh/PI3K/Akt/gelatinase B/MMP-9 pathway, which promotes metastatic dissemination to lymph nodes." (PMID 24473089, 2014). "Subsequently, the increased FN1 expression contributes to the activation of MMP2/MMP9, leading to higher migration and invasion potential of gastric cancer cells, which was manifested by the greater number of metastatic nodules in the nude mice." (PMID 25167886, 2014). "We further explored the influence of tumor invasiveness on the prognostic value of ALDH1A1 expression in gastric cancer by using MMP-9 as an indicator for the invasive potential of individual tumor cells." (PMID 25253129, 2014).